TUBB (tubulin beta class I)
Diseases named in the same sentence as TUBB in open-access papers (continued):
Sharing a sentence is not in itself a finding about the gene and the disease.
infection (5 papers, 2011 to 2024). The state of being infected such as from the introduction of a foreign agent such as serum, vaccine, antigenic substance or organism. "We subsequently used the KEGG pathway analysis and found that the TUBB/Rho/ROCK pathway plays a significant role in the progression of PC through the infection of Escherichia coli." (PMID 32461969, 2020). "The distribution of oocysts number by infected midgut, in tubA and tubB single silencing, showed consistently higher infection intensity than the control groups, although this difference was not significant." (PMID 21912622, 2011). "Moreover, we testified that the TUBB/Rho/ROCK signaling pathway is inseparably correlated with the infection of gut bacteria E. coli." (PMID 32461969, 2020).
metabolic disorder (1 paper, 2024). "The pathway and metabolic disorders mediated by TUBB were validated, and the transcription factors regulating their expressions were identified using the CHIP-seq approach." (PMID 38756529, 2024).
TUBB also shares sentences with these, for which no sentence is quoted: Lissencephaly (3 papers); Acute myeloid leukaemia (1); Alzheimer disease (1); atherosclerosis (1); autoimmune disease (1); AUTS2 syndrome (1); behavioral disorders (1); breast tumor (1); cerebellar agenesis (1); cervical carcinoma (1); cortical dysplasia (1); endometrial cancer (1); esophageal squamous cell carcinoma (1); fibrosis (1); gastric cancer (1); glioblastoma (1); hereditary Lymphedema (1); ischemic stroke (1); legionellosis (1); leukaemia (1); liver cirrhosis (1); Macrogyria (1); Macrothrombocytopenia (1); nematode infection (1); non-melanoma skin carcinoma (1); onychomycosis (1); oral cavity carcinoma (1); ovarian endometrioid carcinoma (1); polymicrogyria (1); prion disease (1).
A further 9 diseases each share a sentence with TUBB in 1 paper.